SLA (Src like adaptor)
Description:
Adapter protein, which negatively regulates T-cell receptor (TCR) signaling. Inhibits T-cell antigen-receptor induced activation of nuclear factor of activated T-cells. Involved in the negative regulation of positive selection and mitosis of T-cells. May act by linking signaling proteins such as ZAP70 with CBL, leading to a CBL dependent degradation of signaling proteins.
Synonyms: SLAP-1; hSLAP; SLAP; SLA1
Tractability: Antibody: its Gene Ontology location is reachable by antibodies, with medium confidence. PROTAC: ubiquitination databases record sites on it.
Gene: Protein-coding gene on chromosome 8 (133,036,728 to 133,102,912, reverse strand). Ensembl gene ENSG00000155926.
Subcellular location: Cytoplasm; Endosome
Subcellular location (Human Protein Atlas): Cytosol; Nuclear membrane
Pathways (Reactome):
Immune System: Negative regulation of FLT3
Gene Ontology:
Molecular function: protein binding; epidermal growth factor receptor binding; phosphotyrosine residue binding
Biological process: regulation of MAPK cascade; signal transduction
Cellular component: COP9 signalosome; cytoplasm; cytosol; nucleoplasm; plasma membrane; endosome
Genetic constraint (gnomAD): Loss-of-function variants: 15 observed, 22.37 expected, observed/expected ratio (o/e) 0.67, 90% interval 0.45 to 1.03. The upper end of that interval is the gene's LOEUF score, 1.03, which puts it in group 4 of 6, group 1 being the genes least tolerant of losing a copy. Missense variants: 229 observed, 247.31 expected, observed/expected ratio (o/e) 0.93, 90% interval 0.83 to 1.03. Synonymous variants: 94 observed, 103.75 expected, observed/expected ratio (o/e) 0.91, 90% interval 0.77 to 1.08.
Homologues: Orthologues: chimpanzee SLA (100% identical), dog SLA (93% identical), rabbit SLA (92% identical), pig SLA (91% identical), rat Sla (88% identical), mouse Sla (88% identical), macaque SLA (87% identical), guinea pig SLA (87% identical), tropical clawed frog sla (60% identical), zebrafish sla1a (48% identical), zebrafish SLA (46% identical), Caenorhabditis elegans nck-1 (17% identical), and 1 more. Paralogues in human: SLA2 (37% identical), GRAP2 (20% identical), GRB2 (18% identical), NCK1 (17% identical), NCK2 (17% identical), GRAP (16% identical), DAPP1 (16% identical), SH2D5 (15% identical), GRAPL (11% identical).
Diseases named in the same sentence as SLA in open-access papers:
SLA is named in the same sentence as 30 diseases in open-access papers, as found by Europe PMC text mining. Sharing a sentence is not in itself a finding about the gene and the disease. The quoted sentences say what the papers report.
autoimmune hepatitis (7 papers, 2009 to 2025). Hepatitis caused by autoantibodies. "in a study had found that Anti-SLA positive autoimmune liver disease patients have a more severe disease clinical course, take longer time to respond to immunosuppression and have more incidences of relapse." (PMID 36741403, 2022). "Furthermore, autoantibodies observed in classical autoimmune hepatitis (e.g., anti-LKM, anti-SLA, anti-ASMA) are not typically detected in patients with APECED–associated autoimmune hepatitis." (PMID 34790633, 2021). "A liver biopsy should be performed in APECED patients with persistent elevation in transaminases and/or bilirubin levels, even when classical serological biomarkers for autoimmune hepatitis are negative (e.g., anti-LKM, anti-SLA, anti-ASMA)." (PMID 34790633, 2021).
influenza (3 papers, 2018 to 2023). An acute viral infection of the respiratory tract, occurring in isolated cases, in epidemics, or in pandemics; it is caused by serologically different strains of viruses (influenzaviruses) designated A, B, and C, has a 3-day incubation period, and usually lasts for 3 to 10 days. "The influenza epitope NSDTVGWSW bound to SLA-1*0401 was used as a control to serve as a supporting reference for positive binding." (PMID 34903918, 2021). "In order to predict whether responses to other influenza proteins are made, it was necessary to know the preferred peptide binding motifs for SLA-1*14:02 and SLA-2*11:04." (PMID 29772011, 2018). "The epitopes were docked with the swine leukocyte antigen-1*0401 (SLA-1*0401) wherein the binding affinity, the binding energy, and the root-mean-square deviation (RMSD) per residue of epitope-SLA complexes formed were determined and compared with the influenza epitope as positive control." (PMID 34903918, 2021).
liver disease (3 papers, 2004 to 2026). "Irrespective of the disease specificity of this marker, it is obvious that testing for anti-SLA/LP will help to reduce the group of cryptogenic liver disease, by recognizing previously misdiagnosed patients with AIH who were seronegative for ANA, SMA or anti-LKM-1." (PMID 15679907, 2004).
leukemia (2 papers, 2015 to 2021). A malignant (clonal) hematologic disorder, involving hematopoietic stem cells and characterized by the presence of primitive or atypical myeloid or lymphoid cells in the bone marrow and the blood. "In our study, we tested several dysregulated genes associated with leukemia by microarray data analysis, including MPL, GADD45g, TOB1, SLA, and ETS1, and mainly focused on MPL, which was reduced by PARP-1 inhibition." (PMID 26314963, 2015).
acute liver failure (1 paper, 2025). Rapid deterioration of liver function causing encephalopathy and coagulopathy. "Notably, in our study, the detection of anti-LKM-1, anti-gp210, and anti-SLA/LP antibodies during the proband’s acute liver failure episode raises the possibility that autoantibody production may occur in the context of NBAS deficiency." (PMID 41132786, 2025).
AIDS (1 paper, 2025). A syndrome resulting from the acquired deficiency of cellular immunity caused by the human immunodeficiency virus (HIV). "People with HIV, particularly AIDS, have lower antibodies production by new infection, thus, AIDS/VL cases produce lower levels of SLA or rK39 antibodies." (PMID 40096173, 2025).
Autoimmunity (1 paper, 2022). The occurrence of an immune reaction against the organism's own cells or tissues. "Percentage of Tregs correlates inversely with markers of disease activity, i.e. anti-SLA and anti-LKM1 autoantibody titers, suggesting that impaired Treg numbers favor liver centered autoimmunity." (PMID 34580437, 2022). "Surprisingly, these animals do not show multiorgan autoimmunity, but develop an AIH-1 like disease, with interface hepatitis, positive ANA and anti-SLA antibodies, suggesting that intact central tolerance is key to prevent AIH-1." (PMID 34580437, 2022).
colorectal cancer (1 paper, 2002). A primary or metastatic malignant neoplasm that affects the colon or rectum. "If cimetidine given to the patients blocked the expression of E-selectin on vascular endothelial cells, even malignant colorectal cancer cells expressing higher levels of sLx and sLa would not be able to adhere to such vascular endothelial cells." (PMID 11870500, 2002).
hepatitis A (1 paper, 2021). "Viral hepatitis serology, including hepatitis A, B, C, and E, and autoimmune serology for ANA, ASMA, anti-LKM1, AMAM2, anti-SLA, were negative." (PMID 33021734, 2021).
hepatitis C (1 paper, 2023). "Anti-SLA positivity is usually found in AIH-1 including overlap syndromes but is not found in association with anti-LKM1 or anti-LC1; it is rarely present in hepatitis C and in drug-induced hepatitis." (PMID 37685291, 2023).
intrahepatic cholangiocarcinoma (1 paper, 2024). A carcinoma that arises from the intrahepatic bile duct epithelium in any site of the intrahepatic biliary tree. "Previous research has shown that overexpression of SLA inhibits intrahepatic cholangiocarcinoma (IHCC) cell growth and induces cell cycle arrest, suggesting a tumor-suppressive role for SLA in IHCC progression." (PMID 38200058, 2024).
leishmaniasis (1 paper, 2025). Infectious disease that is transmitted through the bite of hematophagous female phlebotomine sand flies. "Although rK39 has been reported as more sensitive for acute as opposed to prior leishmaniasis, we observed a strong correlation between SLA rOD and rK39 rOD, indicating similar humoral responses in the HIV+ population." (PMID 40096173, 2025).
papillary thyroid cancer (1 paper, 2022). "Finally, we investigated the expression levels of the common mutated genes (JMJD1C, MUC16, PDZD2, RYR1, and SLA) in papillary thyroid cancer cell lines (K1, TPC-1 and BCPAP) compared to an immortalized normal thyroid epithelial cell line (Nthy-ori 3-1) by qRT-PCR." (PMID 35996174, 2022).
Salmonella Infections (1 paper, 2016). Infections with bacteria of the genus SALMONELLA. "It has been shown that Salmonella infection decreases MHC class II molecules’ expression (swine leucocyte antigen, SLA) by inducing polyubiquitination of SLA-DR in infected cells, limiting pathogen recognition." (PMID 26738723, 2016).
thyroid cancer (1 paper, 2022). "We found that the high impact mutations in JMJD1C, SLA, PDZD2, identified from in-silico analysis in PTC samples, are missing in the thyroid cancer cell lines analyzed, thus suggesting that the altered expression of these genes is due to other regulative biological mechanisms." (PMID 35996174, 2022). "The analysis showed that the gene expression level of JMJD1C, MUC16 and SLA were statistically down-regulated while the gene expression level of PDZD2 and RYR1 were up-regulated in thyroid cancer with respect to normal thyroid tissues." (PMID 35996174, 2022).
thyroid tumor (1 paper, 2022). A benign or malignant neoplasm affecting the thyroid gland. "We aimed to evaluate the common mutated genes (JMJD1C, MALAT1, MUC16, PDZD2, PKHD1, RYR1, SLA and TTN) between thyroid tumor and normal samples." (PMID 35996174, 2022).
type I diabetes (1 paper, 2011). "SLA-1 (AK231553) implicating in immune and type I diabetes had the most number of alternative splicing events in AF that has been known as an important immune organ." (PMID 21906321, 2011).
cancer (7 papers, 2002 to 2025). A tumor composed of atypical neoplastic, often pleomorphic cells that invade other tissues. "An interesting finding related to sialic acid and its effect on treatment is the dependence between the therapeutic effect of drug action and the expression of sialyl Lewis-X (sLx) and sialyl Lewis-A (sLa) epitopes on cancer cells." (PMID 37894470, 2023). "Adhesion of cancer cells via their sLx or sLa antigen to E-selectin on vascular endothelium is considered to lead to metastasis." (PMID 11870500, 2002). "But now, it is known that sialyl Lewis-X (sLx) and sialyl Lewis-A (sLa) antigens are ligands to E-selectin, and sLx and sLa expressed on cancer cells mediate adhesion of the cancer cells to vascular endothelial cells expressing E-selectin." (PMID 11870500, 2002). "They reported that anti-sLx CSLEX and KM93 mAbs did not block adhesion, probably because of the very low levels of sLx expression in the cancer cell lines detected by Western blotting, and that the anti-sLa CA19-9 mAb blocked adhesion of one cancer cell line but not that of another cancer cell line." (PMID 11870500, 2002).
infection (7 papers, 2013 to 2025). The state of being infected such as from the introduction of a foreign agent such as serum, vaccine, antigenic substance or organism. "Additionally, in L. infantum-infected hamsters, we studied the time course of appearance of anti-LieIF2 and anti-LieIF2B antibodies in parallel to anti-SLA along the infection." (PMID 29675401, 2018). "An early activation of cells was also detected in the first week of infection by an increase in expression of activation markers CD25 and SLA-DQ." (PMID 33324583, 2020). "Infection with the ASFV-Georgia 2007 significantly reduced the expression of the cathepsin, impairing the antigen digestion and MHC-II loading, with the SLA-DMA and SLA-DMB downregulation by 12 hpi." (PMID 40817451, 2025). "Following the infection with genotype II ASFV CN/GS/2018, the splenic MHC-II gene expression (SLA-DQA1, SLA-DQB1, SLA-DRA, SLA-DRB1, SLA-DMA, SLA-DMB, and SLA-DOA) decrease in T/B cells, DCs, NK cells, monocytes, macrophages, and neutrophils at 5–7 days post-infection." (PMID 40817451, 2025). "Surprisingly, the infection of the three SECoVs had no obvious impact on the expression of SLA-II and SLA-III molecules, suggesting specific targeting of SLA and antigen presentation molecules by SECoVs." (PMID 35126380, 2021).
tumor (7 papers, 2002 to 2025). "GBP2, a GTPase family member, and SLA are implicated in immune regulation and tumor growth." (PMID 41438620, 2025). "We found that cimetidine treatment was particularly effective in patients whose tumour had higher sLx and sLa antigen levels." (PMID 11870500, 2002). "Treatment with cimetidine markedly reduced the incidence of metastasis and significantly increased survival during a follow-up period of more than 10 years in patients whose tumour cells expressed sLx and sLa epitopes at increased levels." (PMID 11870500, 2002). "While tumor-like cells showed low SRC, SRCIN1, and DAB2IP expression, SLA was predominantly expressed in these cells." (PMID 40917877, 2025).
SLA also shares sentences with these, for which no sentence is quoted: colonic cancer (1 paper); lymphoma (1); non-alcoholic fatty liver disease (1); osteosarcoma (1); overlap syndromes (1); primary biliary cholangitis (1); primary sclerosing cholangitis (1); rheumatoid arthritis (1); viral hepatitis (1); viral infection (1).